STAT2 (signal transducer and activator of transcription 2)
Diseases named in the same sentence as STAT2 in open-access papers (continued):
Sharing a sentence is not in itself a finding about the gene and the disease.
Arrhythmia (1 paper, 2023). Any cardiac rhythm other than the normal sinus rhythm. "Moreover, there have been some studies that suggest an association between STAT2 expression and AF/COVID progression and have illuminated their heart-specific roles in arrhythmias, but the exact mechanisms underlying inflammation-related cardiac dysfunction in AF are still elusive." (PMID 38025532, 2023).
ataxia telangiectasia (1 paper, 2025). Ataxia-telangiectasia is the association of severe combined immunodeficiency (affecting mainly the humoral immune response) with progressive cerebellar ataxia. "SCID, CIDs, DiGeorge syndrome, Wiskott-Aldrich syndrome, Ataxia telangiectasia, Dyskeratosis congenita, ORAI-1 deficiency, CGD, X-linked Agammaglobulinemia, ALPS, STAT1 gain of function, CTLA-4 deficiency, GATA-2 deficiency, TRAPS, FMF, NEMO, TIM3, DOCK8, STAT2, STAT3, PIK3CD." (PMID 41049857, 2025).
atopic dermatitis (1 paper, 2017). "Moreover, the STAT2 expression in skin from patients with atopic dermatitis was comparable to the expression level seen in normal healthy controls." (PMID 28472186, 2017). "We found no changes in the STAT2 expression between lesional and nonlesional atopic dermatitis skin." (PMID 28472186, 2017). "In contrast to psoriatic skin, no alteration in the STAT2 phosphorylation level between lesional and nonlesional skin from patients with atopic dermatitis were observed." (PMID 28472186, 2017). "The phosphorylation level of STAT2 was also examined in lesional and nonlesional skin from patients with atopic dermatitis." (PMID 28472186, 2017).
bacterial pneumonia (1 paper, 2023). Acute infection of the lung parenchyma caused by bacteria (e.g., Streptococcus pneumoniae, Haemophilus influenzae, Chlamydia pneumoniae, Mycoplasma pneumoniae, and Legionella pneumophila). "Type I interferon similarly exacerbates severity of secondary bacterial pneumonia with MRSA, potentially through the activation of macrophage STAT2 (signal transducer and activator of transcription 2)." (PMID 36829255, 2023).
biliary atresia (1 paper, 2024). A rare, biliary tract disease characterized by progressive obliterative cholangiopathy of the intra- and extrahepatic bile ducts, occurring in the embryonic/ perinatal period, leading to severe and persistent neonatal jaundice and acholic stool. "Inborn errors of immunity such as STAT1 and STAT2 in human infants will also be of interest to examine in the context of biliary atresia development." (PMID 39348381, 2024).
cervical squamous cell carcinoma (1 paper, 2022). A squamous cell carcinoma arising from the cervical epithelium. "It has been reported that Jak-STAT signaling pathway can contribute to resistance of cervical squamous cell carcinoma by mediating key activator protein as STAT1/STAT2." (PMID 35392800, 2022).
Chlamydia infection (1 paper, 2022). "Our study identified TLR5, STAT2 and IFNγ as genes significantly associated with the ability of a koala to resolve a Chlamydia infection." (PMID 35510793, 2022).
chordoma (1 paper, 2025). Chordomas are rare malignant tumors arising from embryonic remnants of the notochord in axial skeleton. "In addition, all chordoma cell lines expressed IRF9, which forms a complex with activated STAT1 and STAT2 that stimulates the transcription of ISGs." (PMID 40901948, 2025).
colon adenocarcinoma (1 paper, 2025). "Analysis of TCGA colon adenocarcinoma (COAD) data revealed that STAT2 expression was significantly elevated in tumor tissues compared with normal colon samples (p = 0.00012), a pattern that was also observed for IFNAR1 (p = 0.0046)." (PMID 41440237, 2025).
developmental delay (1 paper, 2023). "WGS identified a rare homozygous single nucleotide transition in STAT2 (c.656C > T), resulting in a p.(A219V) substitution, in a patient displaying developmental delay, intracranial calcification, and up-regulation of interferon-stimulated gene (ISG) expression in blood." (PMID 36753016, 2023).
Gaucher disease (1 paper, 2021). Gaucher disease (GD) is a lysosomal storage disorder encompassing three main forms (types 1, 2 and 3), a fetal form and a variant with cardiac involvement (Gaucher disease - ophthalmoplegia - cardiovascular calcification or Gaucher-like disease). "We found numerous transcription factors that are putative regulators of cytokine expression in a cell-specific context, such as the signaling axes controlled by STAT2, JUN, and NR4A2 as candidate regulators of the monocyte Gaucher disease cytokine network." (PMID 34490253, 2021).
hemophagocytic lymphohistiocytosis (1 paper, 2020). "Severe disease meeting clinical criteria for hemophagocytic lymphohistiocytosis (HLH) remains unusual in STAT2 deficiency, having been reported in only a single individual to date." (PMID 33679716, 2020).
Hepatic steatosis (1 paper, 2024). Steatosis is a term used to denote lipid accumulation within hepatocytes. "Additionally, Stat2 is involved in lipid synthesis by regulating acetyl-CoA carboxylase 1 (ACC1) levels, indicating that Stat2 may be a key transcription factor in the MoMFs subset involved in the alleviation of hepatic steatosis and inflammation in NAFLD by JQF." (PMID 39840059, 2024).
hepatitis B (1 paper, 2021). "It has also been shown that miR-125b is associated with hepatitis B and has been targeted with genes that include IL6, DDX3X, STAT2, STAT3, SMAD4, CDKN1B, MAP3K1 and so on from our results." (PMID 34988221, 2021).
herpesvirus infections (1 paper, 2023). "Despite the high prevalence of herpesvirus infections in the general population and in STAT2-deficient patients, no life-threatening herpesvirus infections were reported in this cohort, besides 1 case of fatal HSE." (PMID 36976641, 2023).
Hypertension (1 paper, 2025). The presence of chronic increased pressure in the systemic arterial system. "Collectively, these findings indicate that under high-salt DOCA-induced hypertension conditions, IRF5 acts as a key regulatory factor, likely interacting with STAT1 and STAT2 within the same regulatory network, contributing to the pathological processes in SSH." (PMID 40332339, 2025). "Notably, while the pro-inflammatory role of STAT family members, such as STAT3, in hypertension has been reported, the role of STAT1/STAT2 in endothelial inflammation remains unclear." (PMID 40332339, 2025).
ileitis (1 paper, 2021). "While our data suggested a neglectable function of STAT2 in coordinating cell death in this mouse model of ileitis, we surprisingly observed that STAT2 influences small intestinal inflammation." (PMID 34141714, 2021). "Of note, additional deletion of STAT2 was not sufficient to restore Paneth cell function but strongly ameliorated ileitis." (PMID 34141714, 2021).
interstitial lung disease (1 paper, 2016). A diverse group of lung diseases that affect the lung parenchyma. "A number of genes, such as Bst2, Rsad2, Ifi44, Oas2 and Stat2, were previously found to be downregulated in pulmonary fibroblasts from IPF patients and from scleroderma-associated interstitial lung disease." (PMID 27428020, 2016).
leukopenia (1 paper, 2015). "This difference between wt and STAT2 KO animals suggests that the Type I IFN production in response to Ads causes leukopenia." (PMID 26291525, 2015).
lung injury (1 paper, 2023). "SNHG4 inhibited METTL3‐mediated m6A level of STAT2 mRNA, which resulted in the alleviated LPS‐induced inflammatory lung injury." (PMID 36565037, 2023).
myocarditis (1 paper, 2023). Myocarditis is a condition that is characterized by inflammation of the heart muscle (myocardium). "Consistent with the downregulation of motif activities of IRF3 and IRF7, peripheral immune cells showed a reduced motif activity level of STAT1::STAT2 and IRF9 at the time of myocarditis." (PMID 37264110, 2023).
Netherton syndrome (1 paper, 2023). Netherton syndrome (NS) is a skin disorder characterized by congenital ichthyosiform erythroderma (CIE), a distinctive hair shaft defect (trichorrhexis invaginata; TI) and atopic manifestations. "Cutaneous viral infections are described in CARD11, LCK, NEMO, GATA2, STK4, DOCK8, and STAT2 deficiencies, STAT1 GOF, Netherton syndrome, WHIM syndrome, and WILD (warts, depressed cell‐mediated immunity, primary lymphedema, and anogenital dysplasia) syndrome." (PMID 37102642, 2023).
ocular hypertensive (1 paper, 2021). "To shed more light on this idea, we measured the changes in the mRNA expression of transcription factors STAT1, STAT2, and STAT3 and found that mRNA levels of all STATs were increased in the retina of ocular hypertensive animals." (PMID 33628191, 2021). "The mRNA expression of STAT1, STAT2, and STAT3 was increased significantly in the retina of ocular hypertensive animals." (PMID 33628191, 2021). "Interestingly, up-regulation of STAT1, STAT2, and STAT3 mRNA was blocked in SNC-121 treated ocular hypertensive animals." (PMID 33628191, 2021).
parasite infections (1 paper, 2021). "In various parasite infections, such as those by T. gondii and Schistosoma japonicum, STAT1 and STAT2 are evoked and mediate the immune response." (PMID 34818332, 2021).
penile cancer (1 paper, 2024). A primary or metastatic malignant neoplasm that affects the penis. "During tumorigenesis phase of penile cancer, the expression evolution of JAK-STAT-SOCS1 axis was characterized by the upregulation of JAK2, STAT1, STAT2, STAT3 and STAT4." (PMID 38774752, 2024).
polymyositis (1 paper, 2023). A rare idiopathic inflammatory myopathy characterized by symmetric proximal muscle weakness and elevated muscle enzymes. "Another study reported that the breakdown of positive IFN-I signatures (top five IFIGs were IFI6, RSAD2, STAT2, IFI44, and IFI27) in whole blood of patients were 73% SLE, 68% SSc, 66% DM, 61% polymyositis (PM), and 33% RA." (PMID 36979843, 2023).
prostate adenocarcinoma (1 paper, 2022). "STAT2 was significantly upregulated in BLCA, CHOL, ESCA, HNSC, kidney renal clear cell carcinoma (KIRC), kidney renal papillary cell carcinoma (KIRP), LIHC, LUAD, LUSC, prostate adenocarcinoma (PRAD), and THCA but significantly downregulated in CHOL." (PMID 36176415, 2022).
rectum adenocarcinoma (1 paper, 2023). An adenocarcinoma arising from the rectum. "We found significant correlations between expression levels of STAT2 and those of STAT3 and cyclin D1, respectively, in tumor samples from colon and rectum adenocarcinoma." (PMID 38001683, 2023).
respiratory failure (1 paper, 2026). The significant impairment of gas exchange within the lungs resulting in hypoxia, hypercarbia, or both, to the extent that organ tissue perfusion is severely compromised.
Splenomegaly (1 paper, 2021). Abnormal increased size of the spleen. "ABX-treated GR STAT2 DKO mice did not display splenomegaly, increased representation of myeloid cells in blood or accumulation of splenic progenitors." (PMID 34378531, 2021).
squamous cell carcinoma (1 paper, 2018). A carcinoma arising from squamous epithelial cells. "The tumor tissue had higher expressions of IRF7 and STAT2 than the normal tissue in the all subject group (p value 0.003 and 0.01, respectively) and in the subgroup of squamous cell carcinoma (SCC) (p value 0.03 and 0.02, respectively)." (PMID 30305853, 2018).
systemic sclerosis (1 paper, 2022). A chronic disorder, possibly autoimmune, marked by excessive production of collagen which results in hardening and thickening of body tissues. "Among the eight TFs selected STAT1 and STAT2 have been previously demonstrated to be constitutively upregulated in monocytes from Systemic Sclerosis patients and to correlate with the expression of STAT-target genes." (PMID 36406275, 2022).
Thrombocytopenia (1 paper, 2021). A reduction in the number of circulating thrombocytes. "As reported, Stat2–/– and Ifnar–/– mice all sacrificed 4–8 days p.i. with weight loss, leukocytopenia, and thrombocytopenia in SFTSV (YG-1) lethal challenge, and variation trends and amplitudes of parameters between the two groups were highly consistent." (PMID 35087498, 2021).
thymic atrophy (1 paper, 2021). "Lymphocytic choriomeningitis virus (LCMV) is reported to induce thymic atrophy via type I interferon and signal transducer and activator of transcription 2 (Stat2)." (PMID 34113341, 2021).
tuberculosis (1 paper, 2020). A chronic, recurrent infection caused by the bacterium Mycobacterium tuberculosis. "In the current study, six genes (IFITM1, IRF9, MX1, OAS1, STAT1, and STAT2) of the “host response signature network” are significantly overlapping with the “human immune response to tuberculosis” pathway with p-value 1.57e-8." (PMID 33362771, 2020).
viral myocarditis (1 paper, 2023). Myocarditis that is caused by an infection with a viral agent. "Whether this points to a failure to detect the disease-causing pathogen, to inflammatory cardiomyopathy/viral myocarditis, or to a hitherto unknown role for STAT2 besides host defense is unknown." (PMID 36976641, 2023).
vitiligo (1 paper, 2023). Generalized well circumscribed patches of leukoderma that are generally distributed over symmetric body locations and is due to autoimmune destruction of melanocytes. "However, FHB therapy significantly hampered the increase of mRNA expression of Jak1, Jak2, Stat1, Stat2, and Stat3 in vitiligo mice, and this inhibitory effect was dose-dependent." (PMID 37575231, 2023). "To further investigate the effect of FHB on the JAK-STAT pathway in vitiligo mice at the transcriptional level, we used qRT-PCR to examine the influence of FHB on the mRNA expression of Jak1, Jak2, Stat1, Stat2, and Stat3 in the lesion region." (PMID 37575231, 2023).
infection (206 papers, 2007 to 2026). The state of being infected such as from the introduction of a foreign agent such as serum, vaccine, antigenic substance or organism. "We observed at least a 107-fold increase in HSV-1 titers relative to healthy cells in STAT2-deficient cells 48 hours after infection." (PMID 36976641, 2023). "rVSV-EBOV has previously been shown to cause lethal infection in Stat2-/-or Ifnar-/- mice, which both lack a functional antiviral interferon (IFN) type I response." (PMID 37433816, 2023). "In murine models, an infection caused by L. amazonensis showed that amastigotes induce a reduction of STAT-2 phosphorylation and an increase of degradation through parasite proteases." (PMID 35774406, 2022). "Knockdown of BCLAF1 led to decreased STAT1 and STAT2 phosphorylation, and increased susceptibility to infection by alphaherpesvirus in lung and brain tissue of mice." (PMID 35803911, 2022). "We found that HMPV infection of STAT2-deficient U6A cells led to reduction of STAT1 and pSTAT1 in a dose-dependent manner with increasing MOI." (PMID 32635475, 2020). "Some of these genes are controlled by Dnase2, Ikbkg, Il17a, Snca, Stat2, Tlr3 and their induction is associated with suppression of infection." (PMID 32793510, 2020). "To date, most of what has been described for STAT2 signaling in pathogenic infections was centered on immune cells, such as macrophages and dendritic cells." (PMID 31009517, 2019). "The STAT2-deficient mice showed a generalized infection, with the MCMV titers in all tested organs being higher than those in the tested organs of the control mice and with the titers being several orders of magnitude higher than those in the control mice." (PMID 29743368, 2018). "MCMV replication was increased in all assessed organs (e.g., liver, spleen, lungs, and salivary glands) of STAT2-deficient mice, resulting in mortality during the first week after infection." (PMID 29743368, 2018). "Additional infection experiments were performed with STAT2-deficient and reconstituted human U6A cells." (PMID 27780205, 2016). "Ad5 replicates to 100- to 1000-fold higher titers in STAT2 KO hamsters than in wild-type ones, and this increased infection causes enhanced pathology." (PMID 26291525, 2015). "Part of this evidence is supported by the fact that the viral load in STAT2 deficient mice was lower than their STAT1 counterparts at multiple time points after infection." (PMID 25768016, 2015). "Conversely, both STAT1 and STAT2 single-deficient mice survived infection with DENV at this same dose of virus, suggesting there are sufficient compensatory mechanisms that protect against DENV infection in the absence of either one of these STAT proteins." (PMID 21379341, 2011). "During the early phase (24 h post infection) of MCMV replication pM27 seems to be the only MCMV-encoded protein significantly reducing STAT2 amounts." (PMID 21698215, 2011). "In addition, rotavirus was associated with STAT1/STAT2 inhibition, which decreased antiviral response in early infection, through the activity of NSP1." (PMID 38791551, 2024). "Therefore, it is significant that we also identified that variation in both STAT2 and IFNγ is associated with infection resolution in the koala." (PMID 35510793, 2022). "On the other hand, a more robust induction of type I and type II interferons and inflammatory cytokines was displayed in the brain of STAT2 deficient mice after infection with AF strains (MR-766, DAKAR 41519) when compared to AS strains (P6-740, FSS13025, PRVABC59)." (PMID 29985932, 2018). "Similarly, DENV infection of AG129 mice, which lacks both type I and type II IFN receptors, or infection of STAT2-deficient mice, lead to fatal infection, associated to viral replication in multiple organs, and vascular alterations, including hemorrhage." (PMID 27610098, 2016).